BCL2 (BCL2 apoptosis regulator)
Diseases named in the same sentence as BCL2 in open-access papers (continued):
Sharing a sentence is not in itself a finding about the gene and the disease.
Burkitt lymphoma (84 papers, 2003 to 2025). A rare form of malignant mature B-cell non-Hodgkin lymphoma. "Recurrent MYC translocations, either alone or in combination with BCL2 rearrangements, are the hallmark of Burkitt’s lymphoma and other mature B-cell neoplasms that are usually associated with an aggressive clinical behavior." (PMID 33651821, 2021). "Untypical for Burkitt’s lymphoma was the relatively strong Bcl-2 expression of B-cells, which is only expressed by about 10% of Burkitt’s lymphomas." (PMID 32375712, 2020). "By obtaining MYC translocation in addition to BCL2 rearrangement, these cells transform to cells that morphologically and phenotypically resemble Burkitt lymphoma or DLBCL, and these patients invariably have a poor prognosis." (PMID 28375188, 2017). "The Daudi and CA46 cell lines are both derived from human Burkitt's lymphoma cells and express high levels of c-Myc and BCL-2." (PMID 26317903, 2015). "The immunophenotypic prototype of Burkitt’s lymphoma is IgM+/CD10+/bcl-2–/bcl-6+ with the Ki-67 proliferation index (PI) nearly at 100%; however, cases with an aberrant immunophenotype (such as bcl-2 expression) exist." (PMID 25364378, 2014). "Although confirmed BHRF1 expression has been shown in only a subset of Burkitt lymphomas, it is plausible that BHRF1 plays a central role in the maintenance of this subset of Burkitt lymphomas as Bcl-2 overexpression is rare in this disease." (PMID 21203485, 2010). "Such regulation was confirmed in EBV-positive Burkitt’s lymphoma Akata cells that express increased levels of endogenous Bcl-2 or mouse lung cancer LKR cells that contain activated ras." (PMID 12477721, 2003). "It is known that Bcl-2 is induced in some Epstein-Barr virus (EBV)-positive Burkitt’s lymphoma cells." (PMID 12477721, 2003). "In addition, gene expression signatures associated with DLBCL/HGBL-MYC/BCL2 (MHG, DHITsig) significantly overlap with those of Burkitt lymphoma (BL)." (PMID 35732829, 2022). "Moreover, ectopic expression of EAF2 also induced apoptosis in a human Burkitt's lymphoma line Daudi, which again was accompanied by decreased BCL-2 protein expression and increased BBC3 transcript level." (PMID 26935903, 2016). "Finally, we demonstrate that icaritin decreases the two critical signal factors, c-Myc and Bcl-2, which promote cell proliferation and survival in Burkitt lymphoma cell." (PMID 24895574, 2014). "We also observed that icaritin was able to decrease Bcl-2 levels, thus shifting the Bcl-2/Bax ratio, and it could obviously reduce c-Myc, a specific molecular target in Burkitt lymphoma." (PMID 24895574, 2014). "Herein, our study demonstrated that icaritin showed cytotoxicity, inhibited the two critical factors, c-Myc and Bcl-2, in Burkitt lymphoma cells, and provided a rational for the further preclinical and clinical evaluation of icaritin for Burkitt lymphoma therapy." (PMID 24895574, 2014). "Should the results for CD10 and BCL6 remain inconclusive, it may be advantageous to perform staining for BCL2, given that Burkitt lymphomas infrequently express this marker; however, it is noteworthy that certain DLBCL cases may exhibit variable expression of BCL2." (PMID 40428800, 2025). "As Burkitt lymphoma lymphoblasts do not normally overexpress BCL-2 or other mutations rendering them resistant to apoptosis, arginase and asparaginase may be useful in the treatment of Burkitt lymphoma." (PMID 30578463, 2019).
Burkitt lymphoma (continued). "Inula viscosa extract supresses cell cycle and proliferation genes (c-MYC, CCND1) while inhibiting anti-apoptotic genes (BCL2, BCL2L1, BCL11 A), demonstrating significant anticancer effects on Burkitt’s lymphoma (BL) cells." (PMID 40214725, 2025). "In the fifth edition of the World Health Organization Classification of Haematolymphoid Tumours: Lymphoid Neoplasms, an algorithm to diagnose the different entities is shown, including DLBCL NOS, Burkitt lymphoma, HGBL NOS, HGBL-11q, and DLBCL/HGBL-MYC/BCL2." (PMID 36497332, 2022). "In these cases, independently of the immunophenotype exhibited by tumor cells, MYC, BCL2, and BCL6 rearrangements should be investigated for the differential diagnosis among HGBL DH/TH, HGBL NOS, and Burkitt lymphoma." (PMID 31388760, 2019). "Bcl-2 protein is highly expressed in DLBCL cell lines and low in Burkitt lymphoma cell lines and Jurkat cell lines." (PMID 31892356, 2019). "In this study, we investigate the antitumor effect and cellular mechanism of a novel Bcl-2/Bcl-xL dual inhibitor, BM-1197, in DCBCL and Burkitt lymphoma cells." (PMID 31892356, 2019). "Together, these data demonstrate that CHK1 is an essential survival factor for Burkitt lymphoma and pre-B ALL cells and that CHK1 inhibition activates BCL2-regulated and BAX/BAK-dependent apoptosis in these cells." (PMID 29167438, 2017). "Translocations between immunoglobulin genes and BCL2, MYC, and BCL1/CYCLIN D1 are found in the majority of follicular Lymphoma (FL), Burkitt`s Lymphoma (BL), and Mantle Cell Lymphoma, respectively." (PMID 24260260, 2013). "Burkitt lymphoma typically tests positive for CD10 while usually testing negative for BCL2, TdT, and CD34." (PMID 40428800, 2025). "To investigate this and identify appropriate cell lines for further in vitro studies, we examined TdT expression in ten DLBCLs (including five cell lines with MYC/BCL2‐DH and an additional line with MYC translocation) and one Burkitt lymphoma cell line by immunocytochemistry." (PMID 41047873, 2025). "Utilizing IHC staining for Bcl‐2, Bcl‐6, and TdT, LBL can be differentiated from Burkitt lymphoma." (PMID 36381035, 2022). "Burkitt lymphoma (inherently BCL2-negative) and a subset of BCL2-negative DLBCL are strongly dependent on MCL1 for survival." (PMID 34576319, 2021). "The neoplastic follicles, but not the high-grade interfollicular Burkitt's lymphoma cells, showed aberrant expression of BCL2." (PMID 21736761, 2011). "Since overactivity of the oncogene myc is obligatory for Burkitt lymphoma, expression of BHRF1 may be necessary to block myc-induced apoptosis, akin to the striking synergy observed between Bcl-2 and myc during B cell transformation." (PMID 21203485, 2010). "The rearrangements involving MYC (MYC-R) are a defining genetic alteration of high-grade B-cell lymphomas (HGBL) carrying BCL2 and/or BCL6 rearrangements, as well as Burkitt lymphoma (BL)." (PMID 37368083, 2024). "The WHO-HAEM4 provisional entity “Burkitt-like lymphoma with 11q aberration” was named as such because of its clinical, morphological (“starry sky pattern”) and immunophenotypic (CD10+/BCL6+/BCL2−/Ki67 high) resemblance to Burkitt lymphoma but lack of MYC rearrangement." (PMID 36460764, 2023). "Bcl‐6 is negative in LBL, while Bcl‐2 and TdT are negative in Burkitt lymphoma." (PMID 36381035, 2022). "In translation, all BCL2-negative malignancies (e.g., Burkitt lymphoma, BCL2-negative DLBCL, or a substantial part of MM) are inherently “resistant” to BCL2 inhibition with venetoclax but still may be effectively targeted with other BH3 mimetics, e.g., MCL1 inhibitors." (PMID 34576319, 2021).
Burkitt lymphoma (continued). "Of great interest, MYC-translocated Burkitt lymphomas showed more sensitive to CS2164 treatment than DLBCL and mantel cell lymphomas, prompting us to investigate the effect of CS2164 alone or in combination with the BCL2 inhibitor venetoclax on the MYC-translocated HGBL-DHL." (PMID 33777762, 2021). "Adams et all investigated in various forms of BCL the expression of BCLW, an anti-apoptotic BCL-2, recently showed by them to be overexpressed in DLBCL and Burkitt lymphoma (BL)." (PMID 29225711, 2017). "This might be related to the absence of antiapopotic factors such as bcl-2, which typically is not expressed in Burkitt lymphoma." (PMID 20356360, 2010). "In our case, tumour cells did not express cytokeratin and bcl-2 but were positive for CD20, CD45 and vimentin, which was more in favour of Burkitt lymphoma." (PMID 41018436, 2025). "It has a Burkitt-like immunophenotype (CD10+, BCL6+, BCL2−) but MYC expression is weak or negative, lacks MYC rearrangement, and is in contrast to Burkitt lymphoma 50% of the cases express LMO2." (PMID 37555980, 2023). "Immunohistochemistry staining in these tumors showed a typical immunoprofile of Burkitt’s lymphoma with positive staining for CD45, CD20, CD10, and BCL-6 and a negative result for BCL-2." (PMID 36634947, 2023). "The Burkitt’s lymphoma cell line Ramos, which is also characterized by MYC translocation and expression of Mcl‐1 but not BCL2, showed a similar sensitivity profile." (PMID 34632715, 2022). "The definition of Burkitt lymphoma (BL) in WHO-HAEM5 remains largely unchanged, describing BL as an aggressive mature B-cell neoplasm composed of medium-sized cells with a germinal center B-cell phenotype CD10+, BCL6+, BCL2-/weak, high Ki67 index (>95%) and an IG::MYC juxtaposition." (PMID 35732829, 2022). "Then, to reach a final diagnosis of Burkitt’s lymphoma, immunohistochemical stainings should provide evidence that lymphomatous cells express CD19, CD20, CD10, and CD79a and no CD3, CD5, Bcl2, and TdT." (PMID 30453922, 2018). "To this end we performed proliferation assays with apoptosis-resistant BCL2 overexpressing MYC-transgenic mouse B cells, pre-B ALL cells lacking BAX/BAK, as well as BCL2 overexpressing Burkitt lymphoma cell lines." (PMID 29167438, 2017). "As BCL2/BCL6 rearrangements by FISH were negative, Burkitt lymphoma (BL) was considered." (PMID 35845210, 2021). "The pathological diagnosis: Based on BCL-2 expression being completely negative, together with the germinal center phenotype, very high Ki-67, and the presence of MYC rearrangement, the pathological diagnosis was aggressive B-cell lymphoma of the cervix, consistent with Burkitt’s lymphoma." (PMID 41561748, 2025). "Immunohistochemical and molecular studies demonstrated typical features of sporadic Burkitt lymphoma: the atypical cells were positive for CD20, CD79a, CD10, CD23, HLA-DR, bcl-6, PAX5, c-myc, and cytoplasmic IgM, but negative for CD3, CD5, CD15, CD30, CD34, TdT, bcl-2, and MUM1." (PMID 34868769, 2021).
lung adenocarcinoma (84 papers, 2005 to 2026). A carcinoma that arises from the lung and is characterized by the presence of malignant glandular epithelial cells. "Based on these findings, it was proposed that A. lanipes extract can inhibit the cell cycle by downregulating CCND1 and causing A549 lung adenocarcinoma cells to undergo apoptosis via modifying the expression of Bax, Bcl-2, and caspases." (PMID 40142097, 2025). "In contrast, the anti-proliferative activity of MCL-1 and BCL-2 is associated with a favorable prognosis effect in some early carcinomas, such as lung adenocarcinoma." (PMID 21401964, 2011). "For example, Chl. could induce a decrease in the viability of A549 (a non-small-cell lung cancer cell line) and CL1–5 (a lung adenocarcinoma cell line) via mitochondria-mediated apoptosis by down-regulating B cell lymphoma 2 (Bcl-2) (Bcl-2), X-linked inhibitor of apoptosis (XIAP), and surviving." (PMID 40933734, 2025). "The results demonstrated that upregulation of PTPRCAP expression in lung adenocarcinoma A549 cells significantly inhibited the protein levels of Bcl-2 compared with the vector groups, but the expression level of BAX and Caspase-3 increased (P < 0.05, n = 3)." (PMID 41411247, 2025). "Exhibits tumor-suppressive effects by inhibiting cell migration and promoting apoptosis via BCL-2 inhibition, downregulated in lung adenocarcinoma tissues." (PMID 40028182, 2025). "For instance, Hedyotis diffusa injection (HDI) has been found to induce ferroptosis in lung adenocarcinoma cells by increasing ROS release through the Bax/Bcl2/VDAC2/3 axis, independently of GPX4 and the PUFA-PLS pathway." (PMID 39944353, 2024). "AZEPS-SeNPs demonstrated a proapoptotic effect on the lung adenocarcinoma A549 cell line by stimulating caspase 3 and Bax (7.08-fold and 6.505-fold, respectively), inhibiting the anti-apoptotic gene Bcl2, and arresting the cell cycle in the S phase." (PMID 39702121, 2024). "Carvacrol nanoemulsion (25, 50 and 100 μg/mL) also decreased ROS and regulated apoptosis via p‐JNK, Bax and Bcl2 and increased Cyt c and activated Cas cascades in human lung adenocarcinoma A549 cells." (PMID 37697969, 2023). "We found that EBLN3P regulates the proliferation of lung adenocarcinoma cells through the miR-655-3p/Bcl2 axis." (PMID 35473552, 2022). "The lncRNA OIP5-AS1 has been shown to modulate Bcl-2 expression by targeting miR-448 in lung adenocarcinoma cells and is inversely related to the patient survival rate." (PMID 35704638, 2022). "The inhibition of LINC00461 reduces the expression of antiapoptotic protein Bcl-2 by increasing the expression of miR-195, thereby promoting apoptosis and increasing the sensitivity of lung adenocarcinoma cells to radiation." (PMID 35783530, 2022). "Silencing the expression of the lncRNA EBLN3P inhibits lung adenocarcinoma cell proliferation and promotes apoptosis by regulating the miR-655-3p/Bcl-2 signaling axis." (PMID 35473552, 2022). "In conclusion, this study demonstrated that EBLN3P silencing inhibits bioactivity and induces apoptosis via the miR-655-3p/Bcl-2 axis, providing a potential therapeutic target for lung adenocarcinoma." (PMID 35473552, 2022). "It has been shown that shear regulators can selectively induce BCL2A1-dependent tumor cells, leading to apoptosis of NSCLC cells, while targeting the intrinsic pathway of BCL-2-related apoptosis can effectively treat lung adenocarcinoma." (PMID 34308964, 2021). "The underlying mechanism of upregulated GLIPR1 cell growth stimulation has been studied in human lung adenocarcinoma A549 cells and correlates with inducing anti-apoptotic Bcl-2 protein expression." (PMID 34142021, 2021).
lung adenocarcinoma (continued). "Another study identified circPUM1 was significantly up‐regulated in lung adenocarcinoma and increased cyclin D1 and Bcl‐2 expression by sponging miR‐138‐5p, thereby facilitating cell proliferation, migration and invasion of lung adenocarcinoma." (PMID 34672397, 2021). "and induced cytotoxic potential against A549 lung adenocarcinoma cell lines by inducing apoptosis through enhancing the activity of caspase-3 and caspase-9 and inhibiting the synthesis of Bcl-2 protein as well as cytochrome c release from mitochondria." (PMID 33808594, 2021). "Long non-coding RNA OIP5-AS1 enhances Bcl-2 expression by reducing miR-448 expression in lung adenocarcinoma." (PMID 32242897, 2020). "Downregulation of Akt phosphorylation was found to increase the expression of Bax and decrease Bcl-2 levels, resulting in a significant increase in lung adenocarcinoma cell apoptosis." (PMID 30388826, 2018). "In this work, we investigated the bcl-2 interactome in human lung adenocarcinoma cells by single-step affinity purification coupled to mass spectrometry protein identification." (PMID 26866271, 2016). "STAT3 phosphorylation inhibitor (Cryptotanshinone, MCE, USA) suppressed STAT3 (Tyr705) phosphorylation and then downregulated Bcl-2 and Survivin expression in lung adenocarcinoma cells." (PMID 27922075, 2016). "Here our research further confirms that sCLU plays an important role on sensitivity to cDDP in human lung adenocarcinoma cells by downregulating Bcl-2, pCas-3, pErk1/2 and pAkt." (PMID 26781643, 2016). "By means of immune-affinity purification/mass spectrometry analysis, we identified 210 proteins in complex with bcl-2 in the H1299 human lung adenocarcinoma cell line stably overexpressing bcl-2 protein." (PMID 26866271, 2016). "Consistent with other studies, we found that DLBCL has the highest percentage of BCL2 amplification (11 %) and lung adenocarcinoma has the highest percentage of MCL1 amplification (20 %)." (PMID 26134786, 2015). "Overexpressing TIMP-1 in a lung adenocarcinoma cell line H2009 resulted in an approximately 3-fold increased expression of Bcl-2, with a marked reduction in apoptosis upon staurosporine treatment." (PMID 26366732, 2015). "Previous studies have shown that bcl-xL anti-sense treatment evokes a strong apoptotic response in lung adenocarcinoma cells that lack the significant expression of Bcl-2." (PMID 24339958, 2013). "Our findings demonstrated that miR-650 confers the docetaxel chemoresistance of lung adenocarcinoma cells via regulating Bcl-2/Bax expression by targeting ING4." (PMID 23991130, 2013). "Enhanced expression of anti-apoptotic Bcl-2 proteins is frequently observed in malignancies of diverse origin, e.g. Bfl-1 in diffuse large-cell lymphoma and Bcl-xL in lung adenocarcinoma." (PMID 17014711, 2006). "To dissect USP1’s functional interactome, we employed Pearson correlation analysis to assess the relationship between USP1 and proliferation/apoptosis and migration-related markers (Ki-67, PCNA, Bcl-2, N-cadherin) using mRNA expression data from TCGA lung adenocarcinoma samples." (PMID 40136409, 2025). "Furthermore, it was determined that FIIN-2 exerts its regulatory effects on Bcl-2 and Bax levels through a dose- and time-dependent manner, consequently activating the apoptosis-related protein Caspase-3 and inducing apoptosis in lung adenocarcinoma cells." (PMID 40755756, 2025). "However, type I and type III ROP16 primary lung adenocarcinoma cells showed a significant upregulation of pro-apoptotic protein Bax and downregulation of anti-apoptotic protein Bcl-2 compared to that of the control (p < .01)." (PMID 39174877, 2024). "BCL2 targeting by miR-497 in A549 is reported in lung adenocarcinoma cells." (PMID 39095857, 2024). "and investigated PSME3, which may affect apoptosis in lung adenocarcinoma cells through the PI3K/AKT/Bcl-2 signaling pathway." (PMID 39346927, 2024).